GPR15LG (G protein-coupled receptor 15 ligand)
Description:
Highly cationic protein that has multiple functions. Acts as a chemotactic factor that mediates lymphocytes recruitment to epithelia through binding and activation of the G protein-coupled receptor GPR15. May be a tumor suppressor; together with SUSD2 has a growth inhibitory effect on colon cancer cells which includes G1 cell cycle arrest. May regulate keratinocyte proliferation. In addition, through activation of Mas-related G protein-coupled receptors (MRGPRs) contributes to pruritogenesis by activating itch-selective sensory neurons and mast cells degranulation. Has antimicrobial activity against Gram-positive bacteria, including Staphylococcus aureus and Actinomyces spec., and Mycoplasma hominis and lentivirus.
Synonyms: AP-57; CSBF; C10orf99; GPR15L; UNQ1833; RLLV1833; FLJ21763; AP57
Tractability: Antibody: UniProt places it where antibodies can reach, with high confidence; its Gene Ontology location is reachable by antibodies, with high confidence; UniProt predicts a signal peptide or a membrane-spanning region.
Gene: Protein-coding gene on chromosome 10 (84,173,801 to 84,185,294, forward strand). Ensembl gene ENSG00000188373.
Subcellular location: Secreted
Gene Ontology:
Molecular function: chemokine activity; G protein-coupled receptor binding; protein binding; receptor ligand activity
Biological process: defense response to fungus; defense response to Gram-positive bacterium; G protein-coupled receptor signaling pathway; lymphocyte chemotaxis; mast cell degranulation; negative regulation of cell cycle G1/S phase transition; negative regulation of cell division; regulation of keratinocyte proliferation; regulation of T cell migration; T cell homeostasis; T cell migration
Cellular component: extracellular region
Genetic constraint (gnomAD): Loss-of-function variants: 6 observed, 6.95 expected, observed/expected ratio (o/e) 0.86, 90% interval 0.47 to 1.64. That is too few expected variants to judge how well the gene tolerates losing a copy. Missense variants: 71 observed, 75.58 expected, observed/expected ratio (o/e) 0.94, 90% interval 0.77 to 1.14. Synonymous variants: 26 observed, 27.71 expected, observed/expected ratio (o/e) 0.94, 90% interval 0.69 to 1.3.
Homologues: Orthologues: chimpanzee GPR15LG (100% identical), dog GPR15LG (63% identical), pig GPR15LG (60% identical), mouse Gpr15lg (54% identical), rabbit GPR15LG (53% identical), rat Gpr15lg (48% identical).
Diseases named in the same sentence as GPR15LG in open-access papers:
GPR15LG is named in the same sentence as 23 diseases in open-access papers, as found by Europe PMC text mining. Sharing a sentence is not in itself a finding about the gene and the disease. The quoted sentences say what the papers report.
psoriasis (14 papers, 2017 to 2025). An autoimmune condition characterized by red, well-delineated plaques with silvery scales that are usually on the extensor surfaces and scalp. "In the human epidermis, peptide expression of G protein-coupled receptor 15 ligand (GPR15L), encoded by the human ortholog C10orf99, was highly induced in the lesional skin of patients with atopic dermatitis or psoriasis." (PMID 35273606, 2022). "In summary, at the present study, we demonstrated that GPR15LG exhibited potent proinflammatory in psoriasis in vivo and in vitro." (PMID 38393364, 2024). "In the present study, the IMQ-induced psoriasis-like mouse model and M5-induced cellular model of psoriasis were employed to investigate the role of GPR15LG in psoriatic inflammation in vivo and in vitro." (PMID 38393364, 2024). "GPR15LG has been shown to modulate a variety of cellular functions and several functions of GPR15LG have been found in the context of psoriasis." (PMID 38393364, 2024). "Consistently, GPR15LG knockdown in vitro significantly downgraded the expression of inflammatory factors in the cellular model of psoriasis." (PMID 38393364, 2024). "We found GPR15LG knockdown down-regulated the expressions of IL-1α, TNF-α, IL-1β and S100A7 in M5-treated HaCaT cells, suggesting a pivotal role of GPR15LG in keratinocyte-mediated inflammation in psoriasis." (PMID 38393364, 2024). "We previously found that GPR15LG protein is highly expressed in psoriasis lesional skin and it positively regulates psoriatic keratinocyte proliferation." (PMID 38393364, 2024). "In the present study, we demonstrated that Gpr15lg (ortholog of GPR15LG) knockdown attenuated the severity of imiquimod (IMQ)-induced psoriasis-like inflammation in mice." (PMID 38393364, 2024). "Results indicated that Gpr15lg knockdown could improve IMQ-induced psoriasis-like inflammation in mice." (PMID 38393364, 2024). "The present study provided evidences that GPR15LG might participate in the progress of psoriasis via regulating keratinocyte-mediated inflammation." (PMID 38393364, 2024). "This line of evidence indicates that GPR15LG is critical for psoriasis development, and it may has proinflammation effect in psoriasis." (PMID 38393364, 2024). "To further investigate whether Gpr15lg can regulate immune response in psoriasis, we detected the level of IL-1α, TNF-α, IL-1β and S100A7 by qRT-PCR and IHC." (PMID 38393364, 2024). "However, to our knowledge, the capability of GPR15LG on regulating psoriasis-like skin inflammation remains largely unknown." (PMID 38393364, 2024).
acute lymphoblastic leukemia (1 paper, 2025). Leukemia with an acute onset, characterized by the presence of lymphoblasts in the bone marrow and the peripheral blood. "Consistent with a lack of agonistic function, a CXCR4-expressing murine acute lymphoblastic leukemia (ALL) cell line, which strongly releases Ca++ upon stimulation with CXCL12, showed no Ca++ release upon GPR15LG treatment." (PMID 40394646, 2025).
metastatic cancers (1 paper, 2025). A carcinoma which has spread from the original site of growth to another anatomic site. "In diseases where excessive CXCR4 signaling exacerbates pathology, such as certain inflammatory and metastatic cancers, targeting GPR15LG could attenuate CXCL12-driven responses." (PMID 40394646, 2025).
T cell lymphomas (1 paper, 2025). "Finally, investigating the effects of GPR15LG on skin manifestations of B cell or T cell lymphomas and its potential role in wound healing will provide valuable insights into its diverse functions." (PMID 40394646, 2025).
cancer (4 papers, 2017 to 2025). A tumor composed of atypical neoplastic, often pleomorphic cells that invade other tissues. "Studies on GPR15LG’s impact on various immune cell subsets and cancer cell types to clarify its broader role in CXCR4 signaling and its potential as a therapeutic target are highly warranted." (PMID 40394646, 2025). "Functional assays, including wound healing and cell migration assays, were conducted across various cell types, including CD4+ T cells and cancer cells, to evaluate the impact of GPR15LG on CXCL12-mediated CXCR4 signaling." (PMID 40394646, 2025). "GPR15LG-based modulators or antagonists might ameliorate skin inflammation and metastatic spread in cancers." (PMID 40394646, 2025). "In addition to its role in inflammatory diseases, emerging evidence indicates an involvement of GPR15LG and its receptors in cancer biology, particularly in colorectal cancer." (PMID 40394646, 2025). "The similarity of GPR15LG’s binding to CXCR4-CXCL12 complexes highlights its potential as a modulator of CXCR4 signaling, potentially influencing immune and cancer cell regulation." (PMID 40394646, 2025). "A key finding is the synergistic effect of GPR15LG with CXCL12, enhancing CXCL12-mediated migration and signaling in both, immune and cancer cells." (PMID 40394646, 2025). "Here, we examined the interactions of GPR15LG with CXCR4 and ACKR3 and their consequences on downstream signaling as well as immune and cancer cell trafficking." (PMID 40394646, 2025). "However, GPR15LG significantly enhanced CXCL12-directed migration, suggesting a potential role in cancer cell migration and disease progression." (PMID 40394646, 2025). "Specifically, GPR15LG enhances CXCL12-mediated CXCR4 signaling synergistically, promoting wound healing and cell migration across various cell types, including CD4 + T cells and cancer cells." (PMID 40394646, 2025). "Whether or not GPR15LG modulates CXCR4-CXCL12 signaling and immune or cancer cell migration remains to be determined." (PMID 40394646, 2025).
GPR15LG also shares sentences with these, for which no sentence is quoted: atopic dermatitis (4 papers); colon cancer (4); dermatitis (3); Psoriasiform dermatitis (3); tumor (3); colitis (2); inflammatory skin disease (2); allergic disease (1); B-cell lymphoma (1); colorectal cancer (1); contact eczema (1); HIV-1 infection (1); inflammation (1); itch (1); lichen planus (1); myocarditis (1); renal failure (1); ulcerative colitis (1).